INS (insulin)
Diseases named in the same sentence as INS in open-access papers (continued):
Sharing a sentence is not in itself a finding about the gene and the disease.
hyperthyroidism (continued). "Conversely, hyperthyroidism can aggravate glycemia by a stimulation of glucose absorption, glycogenolysis and hepatic glucose production as well as enhanced insulin resistance and shortened half-life of circulating insulin concentrations." (PMID 24580798, 2014). "Conversely, hyperthyroidism may lead to enhanced glucose uptake and improved insulin sensitivity." (PMID 40895625, 2025). "In hyperthyroidism, thyroid hormones increase the endogenous glucose production and insulin requirement, alongside decreasing hepatic insulin sensitivity, which may lead to hepatic insulin resistance." (PMID 40731899, 2025). "However, there are also studies that report contradictory findings, indicating that some individuals may exhibit elevated FT3 levels in the context of insulin resistance which leans toward hyperthyroidism." (PMID 40076791, 2025). "Whereas, as a result of hyperthyroidism, glucose depletion increases substantially, increasing insulin demand in peripheral tissues, which is generated by insulin-stimulated glucose oxidation, and ultimately leads to a disruption in hepatic insulin sensitivity." (PMID 37946276, 2023). "Subclinical hyperthyroidism is often associated with metabolic changes, which were observed in SCD1−/− mice (e.g., an increase in energy expenditure, an upregulation of basal thermogenesis, a reduction of body adiposity, and an increase in insulin sensitivity;)." (PMID 33374300, 2020). "The highest significant values of insulin and HOMA-IR were observed in the T2DM coexisting with hyperthyroidism (p < 0.01, p < 0.001)." (PMID 36830883, 2023). "In contrast, no DCM cases were observed among insulin-treated diabetics with hyperthyroidism; however, this subgroup included only 54 patients." (PMID 41153651, 2025). "The overexpression of SMTNL1 or an SMTNL1-mimicking membrane-permeable peptide might counteract the effects of hyperthyroidism selectively in SKM, promoting insulin-sensitizing effects and maintaining the homeostasis of SKM." (PMID 34675885, 2021). "However, hyperthyroid patients constituted a smaller proportion of the cohort, and no cases of DCM were recorded among insulin-treated diabetic patients with hyperthyroidism." (PMID 41153651, 2025). "Neither hyperthyroidism nor eprotirome treatment altered insulin, glucose, or FGF21 levels." (PMID 25172631, 2014). "Although insulin sensitivity and disposal in skeletal muscle increases during hyperthyroidism, glucose intolerance and elevated plasma glucose concentrations have been reported in patients with Graves’ disease or non-insulin-dependent diabetes during experimental hyperthyroidism." (PMID 36902289, 2023). "Plasma valine but not leucine and isoleucine correlated positively with insulin and HOMA-IR in hyperthyroidism." (PMID 35256693, 2022). "In clinical, the glucose-stimulated insulin secretion (GSIS) is elevated in the patient with Grave’s disease (GD, hyperthyroidism), in which the anti-TSHR antibody activates TSHR without TSH5,6." (PMID 29386586, 2018). "In Graves’ disease (GD, hyperthyroidism), the main autoantigen (anti-TSHR antibody) activates TSHR without TSH and it is accompanied with high insulin concentration." (PMID 29386586, 2018).
rheumatoid arthritis (85 papers, 2009 to 2026). A chronic, systemic autoimmune disorder characterized by inflammation in the synovial membranes and articular surfaces. "Prevotella and P. copri specifically have been found to compromise host health, and have been associated with rheumatoid arthritis and insulin resistance." (PMID 29487572, 2018). "Some studies reported its positive association with inflammatory diseases such as rheumatoid arthritis and ankylosing spondylitis, while others demonstrated that P. copri was associated with improved glucose metabolism and insulin tolerance in response to fiber-rich diet." (PMID 39180058, 2024). "Additionally, the role of lactylation in other skeletal behaviors and diseases is gradually being revealed, such as its association with insulin resistance in skeletal muscle, and its roles in tooth development and rheumatoid arthritis, providing new targets for the treatment of these conditions." (PMID 40511385, 2025). "In autoimmune diseases like rheumatoid arthritis (RA), chronic inflammation is linked to increased insulin production." (PMID 39768214, 2024). "The involvement of IL-1 in regulation of insulin sensitivity is highlighted by a recent observation that the IL-1 blocking agent improved IR in rheumatoid arthritis patients with comorbid type 2 diabetes (T2D)." (PMID 37893164, 2023). "Biosimilars are a potential way forward to reduce the cost of long-acting insulin analogues building on the appreciable price reductions seen with biosimilars to treat rheumatoid arthritis." (PMID 34676266, 2021). "We have seen with biosimilars for managing patients with inflammatory diseases such as rheumatoid arthritis that increased competition can lead to low prices for biosimilars, and this should be encouraged for long-acting insulin analogues in Europe." (PMID 34676266, 2021). "For instance, one report showed that chronic treatment with adalimumab for either rheumatoid arthritis or psoriatic arthritis brought about a substantial improvement in insulin sensitivity." (PMID 30914847, 2018). "The most enriched pathways in the pathway analysis were insulin secretion and cell cycle in the L/C group, rheumatoid arthritis and DNA replication in the M/C group, and insulin secretion and DNA replication in the H/C group." (PMID 26745496, 2016). "While this pilot study does not allow us to determine the clinical relevance of HCQ's effect on insulin sensitivity, this degree of improvement in insulin sensitivity may translate into a reduced risk of DM, as suggested by two large epidemiologic studies among persons with rheumatoid arthritis." (PMID 22676348, 2012). "Furthermore, it has been observed in autoimmune diseases such as rheumatoid arthritis, where recent studies show a TNFα inhibitor treatment that reduces insulin resistance, delaying the effects on these rheumatoid arthritis patients." (PMID 35455036, 2022). "Additional significantly enriched terms included fatty acid biosynthesis, (ko00061), rheumatoid arthritis (ko05323), B cell receptor signaling pathway (ko04622), transcriptional dysregulation in cancers (ko05202), insulin signaling pathway (ko04910), and the IL-17 signaling pathway (ko04657)." (PMID 35948882, 2022). "However, the stepwise addition of oral agents and/or insulin contrasts with other diseases, such as rheumatoid arthritis or gout, in which initial management is intense and, subsequently, more modest – a step-down approach." (PMID 23841986, 2013). "On the contrary, however, blocking the action of IL-6 in rheumatoid arthritis patients led to enhanced plasma glucose levels, and IL-6 infusion acutely increased insulin-stimulated glucose disposal in humans, probably via AMP-activated protein kinase in skeletal muscles." (PMID 22615828, 2012).
rheumatoid arthritis (continued). "Also, prolonged fasting (that is, food deprivation for over 2 days) can decrease disease activity in patients with rheumatoid arthritis (RA), improved insulin release and maintained glucose tolerance, and has potential mood-enhancing and pain-relieving effects in chronic pain patients." (PMID 37854337, 2023). "Resistin suppresses the ability of insulin to stimulate cellular glucose uptake and plays a role in obesity, insulin resistance, diabetes, rheumatoid arthritis (RA), and OA." (PMID 30809105, 2019). "In this study, we explored the functional consequences of insulin signaling for the metabolism and phenotype of effector CD4+ T cells in blood and synovial tissue of patients with rheumatoid arthritis (RA)." (PMID 42185247, 2026). "In adults with rheumatoid arthritis, several studies have shown that anti-TNF therapy increases insulin sensitivity." (PMID 31331342, 2019). "Similarly, amelioration of insulin sensitivity was noted in non-diabetic patients with rheumatoid arthritis receiving TNF-α antagonist therapy." (PMID 26633680, 2015). "However, other studies performed with TNFα antagonists on subjects with rheumatoid arthritis and ankylosing spondylitis reveal different results (improvement and no change), but not an increase in insulin resistance." (PMID 25392783, 2014). "Insulin-sensitizing antidiabetic drugs like glitazones of the thiazolidinedione family are other PPAR-γ agonists which increase insulin-mediated glucose transport into the adipose tissue and skeletal muscle and are used as pharmacological ligands for the treatment of rheumatoid arthritis." (PMID 25258478, 2014). "In the present study, we aimed to evaluate whole-body insulin sensitivity in systemic sclerosis (SSc) patients and to compare the results with controls with no autoimmune rheumatic disease (non-ARD) and with patients affected by rheumatoid arthritis (RA)." (PMID 36996012, 2023).
acromegaly (84 papers, 2008 to 2026). Acromegaly is an acquired disorder related to excessive production of growth hormone (GH) and characterized by progressive somatic disfigurement (mainly involving the face and extremities) and systemic manifestations. "Our analysis showed significantly higher fasting glucose and insulin levels in patients with acromegaly compared to controls and an inverse association for the HOMA-IR index." (PMID 40149642, 2025). "In uncontrolled CD or acromegaly, reduced insulin levels associated with pasireotide cannot counterbalance the impaired insulin sensitivity." (PMID 39735646, 2024). "Acromegaly treatment with surgery or medical therapy improves metabolic risk by increasing insulin sensitivity." (PMID 35448486, 2022). "The pathophysiology underlying beta-cell-failure in acromegaly seems similar to that observed during the development of type 2 diabetes where insulin resistance leads to a compensatory hyperfunction of beta-cells." (PMID 31417493, 2019). "Reduced insulin levels associated with pasireotide are unable to counterbalance the reduced insulin sensitivity caused by uncontrolled acromegaly or CD." (PMID 27405306, 2016). "Although this effect could be considered beneficial, in individuals with acromegaly, this effect is associated with ectopic deposits of fat and insulin resistance." (PMID 29724029, 2018). "Significant progress has been made over the years to better understand the mechanisms by which impaired glucose metabolism in patients is uniquely linked to the disease pathophysiology of CD and acromegaly and how pasireotide modulates insulin secretion and sensitivity." (PMID 27405306, 2016). "Beta-cell dysfunction has also been reported in acromegaly, resulting in decreased insulin secretion in response to glucose." (PMID 40142714, 2025). "Acromegaly patients displayed significantly higher fasting glucose (p = 0.037) and fasting insulin concentrations (p = 0.043) than the CG, though the opposite was found in the HOMA-IR index analysis (p = 0.054)." (PMID 40149642, 2025). "An observational study including 210 acromegaly patients was found a strong relationship with insulin levels and colon polyps." (PMID 40167828, 2025). "Patients with CD after pasireotide initiation were more likely to receive insulin as rescue therapy than patients with acromegaly." (PMID 39735646, 2024). "As for individuals misusing GH for recreational and athletic performance-enhancing purposes, GH, IGF-I and insulin levels are increased suggesting that insulin sensitivity is worsened and “iatrogenic acromegaly” is induced, especially if used long-term." (PMID 39665021, 2024). "In summary, the literature findings regarding the impact of SSAs on glucose metabolism in acromegaly suggest a slight deterioration in glucose levels attributed to the inhibition of insulin secretion." (PMID 39119396, 2024). "In the phase III C2402 (PAOLA) trial, patients with acromegaly received metformin, a sulfonylurea derivative (glimepiride), and insulin." (PMID 39735646, 2024). "In acromegaly, excess GH promotes insulin resistance in the liver and peripheral tissues, counteracting the inhibitory effect of insulin on gluconeogenesis and enhancing endogenous glucose production." (PMID 39735646, 2024). "In participants with acromegaly (n=30), mean (min–max) insulin dose increased from 8.3 (2.0–20.0) to 16.7 (4.0–50.0) IU/day; mean change from baseline was +8.4 (–4.0 to 38.0) IU/day." (PMID 38577574, 2024). "Excessive GH levels impact insulin sensitivity, gluconeogenesis, and pancreatic β-cell function, contributing to glucose metabolism disruptions in many individuals with acromegaly." (PMID 39119396, 2024). "In this article, we aim to present the relationship between GH, IGF-1, insulin signaling and glucose homeostasis and how acromegaly affects it." (PMID 36882643, 2023).
acromegaly (continued). "IR, a central feature of acromegaly’s metabolic abnormalities, is thought to be due primarily to GH’s insulin-antagonistic and lipolytic effects." (PMID 36176462, 2022). "IMCL did not change with surgery or in pegvisomant-treated acromegaly patients vs. controls but did decrease with the addition of pegvisomant to SRL therapy and correlated inversely with insulin sensitivity in a combined acromegaly and control cohort." (PMID 36176462, 2022). "In acromegaly, ghrelin levels correlated inversely with insulin levels and HOMA score in most studies, and ghrelin rise was inversely related to the decrease in these with surgery." (PMID 36176462, 2022). "Compared with the control group, the acromegaly group had higher insulin levels after glucose loading, especially in 120 min and 180 min (P < 0.05)." (PMID 34917145, 2021). "In the acromegaly group, the time of the glucose peak (60 min) was inconsistent with that of the insulin peak (30 min)." (PMID 34917145, 2021). "Twelve patients (31.6% [Cushing’s disease, n = 6; acromegaly, n = 6]) randomized to incretin-based therapy received insulin as rescue therapy." (PMID 34275099, 2021). "As the OGTT and insulin releasing test showed, the beta-cell compensatory secretion is not sufficient to inhibit blood glucose elevation, and blood glucose in the acromegaly group is higher than the normal group and peaks at 60 min and lasts for 120 min." (PMID 34917145, 2021). "Despite this, the findings from our study suggest a trend that HbA1c is better controlled with incretin-based therapy versus insulin, particularly in patients with acromegaly." (PMID 34275099, 2021). "After glucose load, the acromegaly group had significantly higher insulin levels than controls, especially in 120 min and 180 min." (PMID 34917145, 2021). "Both insulin sensitivity index and disposal index after glucose load of acromegaly were significantly lower than those of controls." (PMID 34917145, 2021). "In randomized patients, median (range) duration of exposure to long-acting pasireotide in patients with acromegaly was 5.5 (3.7–7.6) months in the incretin-based therapy arm and 5.5 (4.2–8.0) months in the insulin arm." (PMID 34275099, 2021). "The proportion of patients who were receiving insulin at baseline was 6.8% and 10.2% for patients with acromegaly and Cushing’s disease, respectively." (PMID 34275099, 2021). "In patients with acromegaly, myostatin was negatively correlated with GH, fasting insulin, and HOMA-IR." (PMID 34795636, 2021). "GH acts with a bimodal effect on glucose homeostasis, stimulating beta-cell proliferation, insulin synthesis and secretion, but also increasing lipolysis, gluconeogenesis and inducing systemic insulin resistance in active acromegaly." (PMID 33907985, 2021). "Compared with the healthy subjects, patients with acromegaly had significantly increased levels of serum insulin, high-density lipoprotein cholesterol, triglyceride, and growth hormone (GH)." (PMID 33019423, 2020). "Glucose homeostasis is related to disease activity in acromegaly, as higher IGF-I concentrations were found associated to lower insulin sensitivity." (PMID 31417493, 2019). "One potential limitation to the study was that all cats with acromegaly were diabetic and receiving exogenous insulin." (PMID 30620005, 2019). "First-generation somatostatin analogs (SSA) control GH secretion and IGF-I production, thereby lowering disease activity and improving insulin sensitivity in acromegaly." (PMID 31417493, 2019). "As seen from the individual curves, in patients with acromegaly and abnormal glucose tolerance the first-phase insulin response varied widely from 5 to 3,862 pmol × min/L." (PMID 31620090, 2019). "Further, the medical therapies such as somatostatin analogues used in the treatment of acromegaly can also influence the glucose-insulin homeostasis." (PMID 30948746, 2019).